BRCA1 (BRCA1 DNA repair associated)
Diseases named in the same sentence as BRCA1 in open-access papers (continued):
Sharing a sentence is not in itself a finding about the gene and the disease.
breast cancer (continued). "One previous study reported higher RS and PVs in BRCA1/2, but not in other breast cancer–associated genes combined; however, small numbers limited its statistical power." (PMID 33426465, 2021). "BReast CAncer gene 1 (BRCA1) is a significant breast cancer suppressor gene." (PMID 34142659, 2021). "Approximately 72 and 69% of women who harbor BRCA1 or BRCA2 gene mutations, respectively, are likely to develop breast cancer by the age of 80, equating to a 5–20 fold increased risk of developing breast cancer due to the loss of genetic fidelity in other tumour suppressor genes." (PMID 34209669, 2021). "Therefore, hyperactivation of the TGF-ß/SMAD signaling axis induces genomic instability in breast cancer cells with wild-type BRCA1." (PMID 34638302, 2021). "In breast cancer, there are three breast cancer cluster regions in BRCA1: c.179 to c.505 (RHR = 1.46; 95% CI, 1.22–1.74; P = 2 × 10− 6), c.4328 to c.4945 (RHR = 1.34; 95% CI, 1.01–1.78; P = .04), and c.5261 to c.5563 (RHR = 1.38; 95% CI, 1.22–1.55; P = 6 × 10− 9)." (PMID 34711195, 2021). "The nearly identical timing of the “first wave” of mammary tumor development suggests that BRCA1, BRCA2, and PALB2 may be functionally equivalent in mammary tumor suppression." (PMID 33893322, 2021). "Mutations in BRCA1/2 genes, especially germline variations, along with other Fanconi anaemia (FA) pathway genes (such as NBN, RAD54L, ATM), are prototypic molecular alterations that confer HRD in breast cancer." (PMID 34465315, 2021). "In order to better assess the genetic risk to develop cancer in this population, we analyzed the coding regions and the exon–intron junctions of the two main breast cancer susceptibility genes, BRCA1 and BRCA2 through next generation sequencing (NGS) in 51 Burkinabe women affected by breast cancer." (PMID 34717758, 2021). "We then determined the expression of GATA3 in human breast cancer cell lines and found that GATA3 mRNA and protein levels were high in BRCA1 proficient cells (T47D and MCF7) and low or undetectable in BRCA1 deficient (BT20, MDA-MB231, SUM149, and HCC1937) cells." (PMID 34373738, 2021). "Indeed much of the initial observations on PCa heritability arose via a circuitous route from breast cancer studies examining BRCA1 and BRCA2." (PMID 34830851, 2021). "In a large cohort comprising 1554 Brazilian breast cancer patients referred for genetic testing at a single clinical diagnostic laboratory in Brazil, 9.84% were found to be BRCA1 or BRCA2 mutation carriers independent of age." (PMID 34287479, 2021). "Moreover, the reduced copy number of BRCA1, a tumor suppressor gene, can be observed in breast cancer, which indicates the importance of inhibitory genes' CNVs in maintaining the ordinary functioning of the organism." (PMID 33644055, 2021). "During the last decade, BRCA1 and BRCA2 mutations (BRCA1/2) have been screened for hereditary breast cancer and results showed that mutations in BRCA1/2 account for 5% of hereditary breast cancer." (PMID 33402103, 2021). "The aim of the present meta-analysis was to analyze all available studies reporting clinical characteristics of breast cancer gene 1 (BRCA1) gene hypermethylated breast cancer in women, and to pool the results in order to provide a unique clinical profile of this cancer setting population." (PMID 33808555, 2021). "Not all women with mutations in BRCA1 or BRCA2 develop breast cancer and little is known about the factors that influence penetrance, making it difficult to personalize decisions concerning risk-reducing interventions." (PMID 33649363, 2021).
breast cancer (continued). "A more recent study suggested that patients with germline BRCA1/2mut ER+ tumours had a 2.3 times higher risk of disease recurrence and 3.4 times higher risk of breast cancer-related deaths compared to non-carriers." (PMID 33671468, 2021). "Consequently, we examined the relationship between BRCA1 methylation and cyclin E1 protein expression by interrogating the breast cancer dataset of the TCGA." (PMID 34465787, 2021). "All trials that explore the efficacy of PARPi in high-penetrance risk genes (BRCA1/2, PALB2) have shown activity in those genes, definitely introducing in the metastatic breast cancer therapeutic algorithm a new standard treatment for germline mutation carriers." (PMID 33800556, 2021). "HR defects, e.g., due to inactivating mutations in BRCA1 and BRCA2 genes, are exploited in ovarian and breast cancer treatment, where single strand repair inhibitors (PARP inhibitors) as post-chemotherapy maintenance treatment show high efficacy in the HR-deficient subpopulation of patients." (PMID 34616682, 2021). "The penetrance of breast cancer for all BRCA1/2-mutation carriers that have no first-degree relative with breast cancer was 60.4% by age 80 and 63.3% for those with at least one first-degree relative with breast cancer." (PMID 35008272, 2021). "We previously demonstrated that BRCA1 suppresses EMT in breast cancer development." (PMID 34373738, 2021). "Brca1.3 and Brca1.1516 cells have Brca1 deleted from the mammary epithelial luminal progenitor cells and produce tumours that are phenotypically similar to human BRCA1−/− breast cancers." (PMID 33969421, 2021). "In much the same way, few studies found differences in gene expression profiles in BRCA1-linked breast cancer patients compared with non-carriers." (PMID 33525353, 2021). "Though this study reported that central nervous system (CNS) metastases were observed at comparable frequencies in both BRCA1- and BRCA2-mutation carriers, when adjusting for breast cancer subtypes, a significant association with CNS metastases was primarily observed in BRCA2 mutation carriers." (PMID 35008272, 2021). "The present investigation studied the effects of wildtype ADSCs on wildtype and BRCA1-mutated breast cancer cell lines and found no major difference of the effects of CM derived from a panel of ADSCs." (PMID 34228231, 2021). "Taken together, these results indicate that BRCA1 SUMOylation needs further investigation and that BRCA1 may regulate breast cancer in a SUMO-dependent and SUMO-independent manner." (PMID 33968766, 2021). "Overexpression of BRCA1 in prostate and breast cancer cell lines resulted in upregulation of antioxidant proteins, whereas mouse embryo fibroblasts with mutant BRCA1 resulted in downregulation of antioxidant proteins and an increased sensitivity to oxidative stress." (PMID 34222870, 2021). "Breast MRI with contrast has been reported to show a round or oval mass on the chest wall side in BRCA1-associated breast cancer and non-mass enhancement in BRCA2-associated breast cancer." (PMID 34674065, 2021). "BRCA1 has been shown to upregulate Jagged-1 and Notch 1 expression in breast cancers." (PMID 33924995, 2021). "Finally, lifestyle modifications in BRCA1/2+ breast cancer survivors, including physical activity and diets rich in flavonoids (in fruits and vegetables), revealed decreased TNF-α levels." (PMID 34950252, 2021). "In summary, we have found that CDK2 inhibition may sensitize BRCA1 mutant breast cancer cells to PARP inhibitors." (PMID 34465787, 2021). "Patients with the PALB2 mutation were most likely to have personal breast cancer only and no family history of prostate and ovarian cancer when comparing with BRCA1 carriers." (PMID 34439348, 2021). "Moreover, BRCA1 and ΔNp63 contribute to the regulation of stemness and differentiation signaling in breast cancer by joint up-regulation of the Notch ligand Jagged-1 (JAG1)." (PMID 34638302, 2021).
breast cancer (continued). "A family history of ovarian cancer—especially those characterized by BRCA1 and BRCA2 mutations—might also induce a greater risk of breast cancer." (PMID 34503097, 2021). "To confirm the cytotoxic effects of inhibition of PDGFR and PKCα on BRCA1-deficient human breast cancer cells, we screened six widely used cell lines including two BRCA1 WT luminal lines, T47D and MCF7; two BRCA1 WT basal lines, MDA-MB231 and BT20; and two BRCA1 mutated lines, HCC1937 and SUM149." (PMID 33478572, 2021). "Furthermore, Pdgfrβ mRNA levels in p18−/−;Brca1+/− mammary tumors strongly correlated with EMT and stem cell signatures, in agreement with the data derived from IHC and published elsewhere." (PMID 33478572, 2021). "The 10-year cumulative risk of contralateral breast cancer is 5.1% for non-carriers, 21.1% for patients with BRCA1 mutation, and 10.2% for BRCA2 mutations." (PMID 33996049, 2021). "Results presented in this study confirm this notion for BRCA1-mutant breast cancer cells." (PMID 33412559, 2021). "In breast cancers, most of the studies have reported worse clinical prognosis for patients with BRCA1 mutations compared with BRCA2 mutation carriers and non-carriers." (PMID 33525353, 2021). "The Consortium of Investigators of Modifiers of BRCA1/2 (CIMBA) reported a ratio of 3.5:1 excess of BRCA1 CNVs compared to BRCA2, among 18,435 breast cancer cases with BRCA1 PVs and 11,351 with BRCA2, ascertained from 69 centers in 49 countries on 6 continents." (PMID 34413315, 2021). "Besides the BRCA1 and BRCA2, mutations in other rare and highly penetrant genes are linked with increased risk of breast cancer development." (PMID 33540843, 2021). "The risk of male breast cancer is also increased in the male carriers of such variants, particularly those in BRCA2, where the lifetime risk is approximately 8–10% when compared to BRCA1, where the risk is in the order of 1%." (PMID 34771713, 2021). "In conclusion, the present data indicate that BRCA1/BRCA2 sequencing may be considered for postmenopausal breast cancer patients having a family history of cancer." (PMID 34287479, 2021). "In recent review, prevalence of BRCA1/2 status in breast cancer varied across the globe." (PMID 33649982, 2021). "In addition, RPS6P−/− breast cancer cells with a BRCA1-defective background demonstrated olaparib sensitivity." (PMID 35008473, 2021). "Second, some clinical risk factors like Ki-67 index and BRCA1- and BRCA2- related mutation as well as high 21-Gene Recurrence Score (21-GRS) which have been proved to be related to worse OS in patients with breast cancer were unavailable in the SEER database." (PMID 35116010, 2021). "Furthermore, it is not accurate for use in the known carriers of pathogenic variants in BRCA1 or BRCA2, or other breast cancer susceptibility genes." (PMID 34771713, 2021). "Longer use of OC, especially before the first full-term pregnancy, was also associated with an increased risk of breast cancer for both BRCA1 and BRCA2 mutation carriers (HR = 1.49; 95% CI = 1.05–2.11 for BRCA1 subjects and HR = 2.58; 95% CI = 1.21–5.49 for BRCA2 subjects)." (PMID 33925599, 2021). "Therefore, in this study, we aimed to evaluate the risk assessment for BRCA1- and BRCA2- associated breast cancer using fuzzy logic and neural networks systems." (PMID 34828379, 2021). "The BRCA1 promoter is methylated while the BRCA1 copy number is reduced in sporadic breast cancer." (PMID 33644055, 2021). "Unlike high expression of cyclin E1, which is predictive of poor survival, 19q12 (CCNE1) amplification had no prognostic value for overall survival in BRCA1 mutated breast cancer." (PMID 34465787, 2021). "In 1990, BRCA1 (located on chromosome 17) was identified as a classical tumour suppressor gene (TSG) due to the loss of a wild-type (wt) allele during tumorigenesis, being the first TSG associated with hereditary and sporadic cases of basal-like breast cancer." (PMID 34298653, 2021).
breast cancer (continued). "The patient had no identifiable germline breast cancer predisposition variants, in concordance with earlier clinical testing for BRCA1 and BRCA2 germline mutations." (PMID 34711268, 2021). "In addition, we demonstrated increased sensitivity to a PARP inhibitor in a CTC culture derived from a patient with a pathogenic somatic BRCA1 mutation, highlighting the unique role of PARP inhibition for patients with somatic BRCA1/2 mutant breast cancer." (PMID 33520111, 2021). "BRCA1 is the key molecule in breast cancer and is mainly expressed at low levels in breast cancer." (PMID 34457116, 2021). "The median AUC of the BRCA1 mutant type cancer cell lines was smaller than that of the wild-type, indicating that an FLT3 inhibitor (sunitinib) has potential therapeutic effects for hereditary breast cancer and ovarian cancer with a BRCA1 mutation." (PMID 33627666, 2021). "The median age was 43 years at the time of diagnosis (75 patients with breast cancer enrolled in the study were negative for the 5 most common BRCA1 mutations)." (PMID 33918338, 2021). "Finally, sodium arsenite exposure was shown to increase BRCA1 promoter methylation in a human breast cancer cell line in vitro, also reducing DNA repair capacity (see Section 3.1)." (PMID 34681626, 2021). "Most of the pathogenic variants were in BRCA1 (n = 16, 23.2%), and the majority (n = 54, 78.3%) of such patients had a positive family history of breast cancer; only 2 (13.3%) of the 15 patients with no family history had a pathogenic variant." (PMID 34290354, 2021). "Despite guidelines that recommend genetic testing for patients at increased risk of carrying a pathogenic variant in a breast cancer gene (e.g. BRCA1, BRCA2, CHEK2, PALB2, ATM) not all eligible patients are referred for genetic testing." (PMID 33933926, 2021). "Ten-year cumulative contralateral Breast Cancer (CBC) risks were 21.1% for BRCA1, 10.8% for BRCA2 mutation carriers and 5.1% for non-carriers." (PMID 34356066, 2021). "Further, a specific founder mutation in BRCA1 in Western Sweden has previously been defined by and may possibly contribute to MPM in the breast cancer population in Western Sweden." (PMID 34057285, 2021). "Categorizing age at first breast cancer diagnosis for BRCA1 heterozygotes resulted in HRs per SD of the ER-negative PRS313 of 1.22, 95% CI (1.14–1.31); 0.99, 95% CI (0.90–1.09);, and 1.03, 95% CI (0.86–1.24) for ages <40 years, 40–50 years, and ≥50 year respectively." (PMID 34113011, 2021). "Thus, in BRCA1-mutant breast cancer cells, P-cadherin expression is increased, contributing to the invasive and metastatic potential of these cancer cells." (PMID 35008272, 2021). "Moreover, we queried the mRNA expression of genes in the METABRIC 1584 breast cancer sample sets and found a significant inverse correlation between BRCA1 with PDGFRβ and PKCα mRNA levels." (PMID 33478572, 2021). "Additionally, the PV status of all 5060 women with breast cancer tested for BRCA1/2 was included in order to determine the effect of extended panel testing in women stratified by MS." (PMID 34439310, 2021).
breast cancer (continued). "After excluding L63X founder mutation, the proportion of patients with a family history of ovarian cancer and germline BRCA1 mutations outside the OCCR was lower and the proportion of patients with a family history of breast cancer and germline BRCA1 mutations within the OCCR was relatively lower." (PMID 34356066, 2021). "LncRNA Xist, which is dependent on the production of BRCA1 and may participate in regulating breast cancer development, is highly expressed in BRCA1-like breast cancer as a predictive biomarker." (PMID 34178980, 2021). "In this study, we found near 80% of the BRCA1-deficient mouse mammary tumors are ER and PR double negative, while 60% of the tumors show detectable expression level of ERBB2, which is inconsistent with the human BRCA1 related breast cancers." (PMID 34815798, 2021). "Analysis of all BRCA1/2 cases showed no reduction in the risk of developing breast cancer in the RRSO-treated group, although the BRCA2 mutation-bearing group showed an 83% reduction in risk at < 50 years of age." (PMID 32862296, 2021). "It has been also demonstrated that some sporadic breast cancers harbor defects in the HR and FA pathway, in the absence of a germline BRCA1 or BRCA2 mutation, a condition referred as BRCAness." (PMID 33808562, 2021). "Collectively, our results suggest that elevated ROS rather than DNA damage may be responsible for the increased apoptosis of the Brca1;Palb2 double KO MECs and therefore may contribute to the reduced mammary tumor formation in these mice." (PMID 33893322, 2021). "Among cases, a first diagnosis of TNBC rather than any other breast cancer subtype was associated with BRCA1 for both AA and EA patients." (PMID 33479248, 2021). "It is found that BRCA1 may suppress the BPA-induced human breast cancer cell proliferation in vitro and in vivo." (PMID 34311656, 2021). "Data for the Asian population showed that the prevalence of BRCA1/2 germline mutations was 9.8% in South Korean non-familial high-risk breast cancer patients and 9.4% in Chinese hereditary breast-ovarian cancer (HBOC) families." (PMID 34917121, 2021). "In breast cancer patients, other molecular changes, such as epigenetic silencing of BRCA1/2 and other genes, may be present." (PMID 33918338, 2021). "It has been demonstrated that UBE2T has a crucial role in the regulation of BRCA1 in breast cancer." (PMID 33313822, 2021). "However, the potential impact of BRCA1/2 mutations on the individual cell populations within the unique tumor microenvironment (TME) and their relation to breast cancer has been understudied." (PMID 33540843, 2021). "Reanalysis of publicly available cancer genomic data also suggested that of the four cancer histotypes that commonly exhibit pathogenic BRCA1/2 mutations, BRCA-mutant breast cancers tended to express higher POLQ mRNA than for BRCA-gene wild type breast cancers." (PMID 34140467, 2021). "Although data are limited, HRT does not seem to be associated with relevant increases in breast cancer risk according to the available studies, especially for BRCA1/2 mutation carriers who had RRBSO." (PMID 33885953, 2021). "Some clinically relevant genes may encounter pseudogenes, such as KRAS for colorectal cancer and BRCA1 for ovarian cancer and breast cancer." (PMID 33916923, 2021). "We have assessed the frequency of potentially actionable breast cancer gene variants in a large series of women with breast cancer comparing rates of detection of non-BRCA PVs with BRCA1/2 at different BRCA1/2 likelihood scores." (PMID 34439310, 2021). "In contrast to IBTR, the rate of contralateral breast cancer was significantly higher among BRCA1/2 variant carriers than among noncarriers regardless of BCT or mastectomy." (PMID 33890992, 2021).